IL22 (interleukin 22)
Diseases named in the same sentence as IL22 in open-access papers (continued):
Sharing a sentence is not in itself a finding about the gene and the disease.
liver disease (continued). "Also, IL-19, IL-22, and IL-24 participate in wound healing, an event present not only in the skin but also in liver disease as a first step for fibrogenesis, cirrhosis, and liver failure." (PMID 29892294, 2018). "The roles of IL-22 in liver diseases have been investigated widely." (PMID 28659927, 2017). "Therefore, clinical trials examining combination therapy with IL-22 for the treatment of patients with liver disease are warranted." (PMID 24623532, 2014). "Taken together, IL-22 may directly or indirectly contribute to liver disease pathogenesis by promoting the migration of inflammatory cells into the liver, which can increase T cell-induced hepatocyte injury." (PMID 24623532, 2014). "It is focused mainly on the IL-22 intracellular signaling and its influence on liver diseases." (PMID 24623532, 2014). "All these results indicated that IL-22 may be an more effective and safer therapy for viral hepatitis and other liver diseases." (PMID 24623532, 2014). "To date, there have been few studies on IL-22 in human liver disease." (PMID 23372820, 2013). "We next investigated whether distinct etiologies of liver diseases in the patient cohort under investigation affected IL-22 serum levels." (PMID 22967278, 2012). "Notably, the course of hepatic disease in this context depends on robust leukocyte infiltration, which is at least in part dependent on IL-22." (PMID 22967278, 2012). "Next, we were interested whether IL-22 serum levels are stably increased in the course of liver disease." (PMID 22967278, 2012). "Moreover,elevated IL-22 serum levels were more frequent in patients with ascites, hepatorenal syndrome (HRS) and spontaneous bacterial peritonitis as compared to patients without these complications." (PMID 22967278, 2012). "Also involved in TB and liver disease, IL-22 inhibits intracellular growth of Mycobacterium tuberculosis in human monocyte-derived macrophages and is associated with acetaminophen-related hepatotoxicity and resolution of acute-on-chronic liver failure (ACLF) in small animal models." (PMID 34440095, 2021). "As the main cell source of intrahepatic IL-22, ILC3s might play important roles in liver diseases." (PMID 28659927, 2017). "However, the role of IL-22 in the liver whether as inducer or suppressor of fibrosis is dependent on the etiology of hepatic disease." (PMID 27681697, 2016). "The effect of hepatic IL-22 as whether pro- or anti-fibrotic is poorly understood, the available data are conflicting and the role of the cytokine in liver fibrogenesis appears to be dependent on the etiological context of liver disease." (PMID 27681697, 2016). "IL-22 may have promise as a potential therapeutic agent for liver diseases." (PMID 24623532, 2014). "Numerous studies have indicated that IL-22 administration activates hepatic STAT3 signaling and ameliorates several liver diseases, including autoimmune hepatitis, viral hepatitis, drug-induced liver injury, alcoholic fatty liver and steatohepatitis." (PMID 36193422, 2022). "The role of IL-22 in liver disease has been widely studied, and since the major cellular source of IL-22 in the liver is ILC3, ILC3 may play an important role in liver disease." (PMID 33790913, 2021). "IL-22 over-expression in the liver induced by HGD of IL-22 cDNA expressing plasmid protected the liver from various toxins induced damage, which indicates that IL-22 has the therapeutic potential in the treatment of human liver disease." (PMID 28912718, 2017). "Interleukin-22 (IL-22), a member of the IL-10 cytokine family produced by T cells, innate lymphoid cells (ILCs) and macrophages, plays context-dependent roles in diverse non-neoplastic liver diseases, exhibiting dual pro- and anti-inflammatory functions across disease models." (PMID 41562076, 2025). "However, the role of IL-22 in liver disease is not unequivocal." (PMID 22967278, 2012).
liver disease (continued). "Despite the clear evidence from animal models, we do not yet know to what extent IL-22 secreting T cells participate in different stages of human liver disease, their impact in tissue, or to what extent measurement of such cells in blood or liver may vary or correlate with clinical outcome." (PMID 23181064, 2012). "Intrahepatic enrichment of IL-22 in chronic hepatitis B (CHB) or C (CHC) patients, while not directly impacting the replication of HBV and HCV in hepatocytes, suggests a crucial role of the cytokine in the progression of liver disease." (PMID 39156888, 2024).
Hepatitis (43 papers, 2011 to 2025). Inflammation of the liver. "In the AIH model of ConA-induced hepatitis, CD4 T cells are the primary source of IL-22, and IL-22 deficiency has been reported to exacerbate hepatitis." (PMID 40616144, 2025). "First observations already underlined such functions in 2004, where depletion of IL-22 was associated with increased severity of ConA- and CCl4-induced hepatitis." (PMID 33851257, 2021). "In 2004, professor Bin Gao's team confirmed that IL-22 mRNA and protein expression was significantly increased in T cell-mediated hepatitis caused by ConA." (PMID 30515423, 2018). "Mice that are deficient in RBP-J, a key mediator of Notch signaling, are highly susceptible to the detrimental immunopathology associated with Con A-induced hepatitis with little IL-22 production." (PMID 23956763, 2013). "In many of these experimental models, such as conA-mediated hepatitis, IL-22-deficient mice are extremely more susceptible than are wild-type controls, with highly elevated aspartate transaminase (AST) and alanine transaminase (ALT) levels and large regions of necrotic tissue." (PMID 34868019, 2021). "Therefore, the role of IL-23 in the induction of IL-22 and IL-17 production and liver damage during Con A-induced hepatitis using IL-23p19- and IL-17-deficient mice was investigated." (PMID 23956763, 2013). "IL-22 is also protective in many different inflammatory settings in the liver, including conA-mediated hepatitis, which is mediated by host IFNγ; liver injury induced by carbon tetrachloride or acetaminophen; ischemia-reperfusion; and viruses." (PMID 34868019, 2021). "The most prevalent view is that IL-22 possesses protective roles in liver injury during hepatitis, which relieves tissue damage by counteracting the destructive nature of immune responses." (PMID 34944732, 2021). "To summarize, IL-22 has dual effects in chronic liver inflammations, while the role of IL-22 in acute liver infections is considered to be protective overall." (PMID 33851257, 2021). "Although another report detected an equal protective effect of administered recombinant IL-22 during APAP hepatitis, the authors of this report found an increased susceptibility of IL-22TG mice to this method of hepatitis induction." (PMID 33851257, 2021). "IL-22 has been reported to show hepatoprotective effects via antiapoptotic activity and prosurvival pathways in hepatitis." (PMID 28050571, 2016). "Numerous studies have shown that IL-22 mediates a physiologic response to repair local tissue damage in experimental models such as hepatitis, pancreatitis, colitis, and thymic injury." (PMID 26784895, 2016). "Introduction of IL-22 expressing Th17 cells prior to hepatitis induction has been shown to improve liver damage in mice." (PMID 28050571, 2016). "STAT4 is important for IL-22 production, which plays a pathological role in IL-17-dependent hepatitis." (PMID 23990947, 2013). "Nonetheless, although IL-22 shows a marked protective role in Con A-induced hepatitis, IL-22 also enhances the pro-inflammatory activity of TNF-α expressed in the liver after transfer of HBV-specific T cells." (PMID 23956763, 2013). "One study has also found that peripheral Th17 cells from CHB patients have little capacity to produce IL-22, a cytokine which has been demonstrated to protect against T-cell-mediated hepatitis." (PMID 23448394, 2013). "Additionally, IL-22 overexpression ameliorated ConA-induced hepatitis, suggesting the possibility of hepatitis treatment via Th22 induction." (PMID 40616144, 2025). "In a recent prospective cohort study, IL-22 levels were significantly increased in alcohol-associated non-severe hepatitis and alcohol-associated severe hepatitis patients compared to the control group." (PMID 38667527, 2024). "The role of IL-22 in HBV induced-liver inflammation remains controversial." (PMID 32760208, 2020). "For instance, IL-22 has protective roles in ConA-induced hepatitis." (PMID 24586644, 2014).
Hepatitis (continued). "Numerous experiments have also shown that IL-22 plays a protective role in mice with hepatitis." (PMID 23956763, 2013). "Notably, previous reports have emphasized that IL-22 produced by Th17 cells can act protectively in various acute hepatitis models, although NKT cells are pathogenic in the development of Con A-induced hepatitis." (PMID 23626860, 2013). "Furthermore, the number of RORγt+ hepatic ILCs was also decreased, and exogenous IL-22 administration protected RAG-2−/− × RORγt−/− mice from hepatitis." (PMID 23626860, 2013). "IL-22 enhances the hepatocyte survival in a T cell-mediated murine hepatitis model." (PMID 23519428, 2013). "In addition, exogenous IL-22 injection protected RAG-2−/− × RORγt−/− mice from CCl4-induced hepatitis to some extent." (PMID 23626860, 2013). "Treatment with IL-22 using gene delivery provided protection during experimental hepatitis." (PMID 21789181, 2011). "Liver-targeted delivery of the IL-22-ApoA1 fusion gene by penetratin-based hybrid nanoparticles relieved liver injury, evaded immune responses, promoted hepatocyte regeneration, and relieved oxidative stress and mitochondrial dysfunction in a concanavalin A-induced hepatitis mouse model." (PMID 34944732, 2021). "Since HFD-related gut barrier dysfunction is a source of gut, VAT and liver inflammation and IR and AhR may have beneficial effects on the intactness of the gut epithelial barrier mediated by IL-22, we investigated similar immune-mediated mechanisms for indigo in glucose homeostasis." (PMID 30944419, 2019). "In addition, Zhang and colleagues indicate that intravenous injection of IL-22 could enhance liver regeneration in mice with Con A-induced hepatitis after partial hepatectomy by augmentation of PCNA and cyclin D1 levels." (PMID 28578410, 2017). "Experimental models have shown that IL-22 prevents tissue destruction and mediates regeneration of damaged tissue by inducing expression of genes regulating proliferation, survival, and wound healing, ameliorating tissue damage in colitis, hepatitis, and lung fibrosis." (PMID 27303405, 2016). "Moreover, IL-22/STAT3 has an anti-fibrotic function in T cell-mediated murine hepatitis." (PMID 27819314, 2016). "In addition, systemic involvement in AGEP such as hepatitis may be due to circulating IL-17 and IL-22." (PMID 26783390, 2015). "Therefore, RORγt+ hepatic ILCs may be involved in clinical hepatitis and represent a candidate for a target of novel treatment for clinical hepatitis since IL-22 can prevent and repair liver damage." (PMID 23626860, 2013). "Although IL-6 has the ability to induce IL-22 production, and IL-6-deficient mice were shown to be highly susceptible to liver damage, these mice were reported to have no impairment in IL-22 expression during Con A-induced hepatitis." (PMID 23956763, 2013). "Administration of rmIL-22 or IL-22 adenovirus activates hepatic STAT3 signaling, therefore alleviating alcohol-induced hepatitis and steatosis." (PMID 34944732, 2021). "It has been reported that IL-22 induces STAT3 activation in the liver and IL-22 blockade significantly reduces hepatic STAT3 activation in T cell-mediated hepatitis." (PMID 29383167, 2017). "IL-22 produced by CD4+ T cells is cytoprotective during lymphocytic choriomeningitis virus infection in mice, where it reduces the development of hepatitis." (PMID 27303405, 2016). "The intestinal effects of IL-22 include regulating AMP expression, microbiota, and gut barrier function that is pivotal in ameliorating alcohol induced translocation of gut-derived bacterial pathogens and liver inflammation." (PMID 37908362, 2023). "Mice expressing IL22 under an albumin promoter do not develop liver inflammation but are resistant to ConA T cell-mediated hepatitis." (PMID 33452360, 2021). "The reason why ROR KI/w mice or Rag2KO mice fed with HFD developed NAFLD but not NASH was that the ILC3 activated by HFD secreted IL22, and the effect of IL22 was thought to prevent hepatitis." (PMID 33790913, 2021).
Hepatitis (continued). "Furthermore, Notch signaling pathway promoted IL-22 production by both CD4+ T cells and ILC22 in Concanavalin A-induced hepatitis and chronic viral hepatitis." (PMID 30473538, 2018). "Although the study suggested Notch-mediated IL-22 protected RBP-J−/− mice from ConA-induced hepatitis, more recent study on experimental autoimmune uveoretinitis revealed a key pathological role of RBP-J/Notch-induced IL-22 production in late phase of the disease." (PMID 27800305, 2016). "Moreover, STAT3 could also be activated by several other factors including IL-22, IL-10, ECG and hepatitis viral proteins, suggesting that further well designed studies should be conducted to explore the association between them and the risk of ATDH." (PMID 25789467, 2015). "Surprisingly, RAG-2−/− × RORγt−/− mice developed significantly severer CCl4-induced hepatitis compared with RAG-2−/− mice, in accordance with the fact that hepatic ILCs failed to produce IL-22." (PMID 23626860, 2013).
Autoimmunity (39 papers, 2011 to 2025). The occurrence of an immune reaction against the organism's own cells or tissues. "In line with these mouse data, in the DC/T-cell co-cultures we observed potent additive effects of IL-7 and TSLP on production of Th17-associated cytokines IL-17, IL-21 and IL-22 that can strongly stimulate autoimmunity." (PMID 26110994, 2015). "Increased IL-22 and IL-23R expression during Th17 differentiation has recently been suggested as a signature for pathogenic Th17 cells that can induce autoimmunity in animal models." (PMID 24349309, 2013). "The recently discovered Th17 cells, a subtype of CD4+ T-helper cells mainly producing IL-17 and IL-22, have initially been linked to host defense against infections and to autoimmunity." (PMID 21197451, 2011). "The dynamic balance between Th17 and Treg cells is essential for maintaining immune homeostasis: Treg cells expressing IL-10 and TGF-β establish pregnancy tolerance, while Th17 cells producing IL-17, IL-21, and IL-22 are associated with pregnancy loss and autoimmunity." (PMID 40894398, 2025). "Therefore, the identification of receptors and associated signaling mediators regulating IL-22 expression could represent an important goal of the ongoing research in inflammation and autoimmunity." (PMID 33178223, 2020). "Helper T cells 17 (Th17) are a subpopulation of T cells that are capable of secreting IL-17, IL-21, and IL-22, which mainly play important roles in autoimmunity and defense response against extracellular bacteria or fungi." (PMID 38349411, 2024). "PKM2 promotes Th17 cell differentiation (Th17 defense, the production of IL-22 and IL-17 cytokines and inflammation/autoimmunity)." (PMID 38674024, 2024). "Type III IFN and cytokines IL-10, IL-22, and IL-26 are ligands for this receptor, thereby linking the genetic overdosage in trisomy 21 with autoimmunity and autoinflammation in DS." (PMID 39457216, 2024). "Type 3 immunity is composed of RORγt (retinoic acid-related orphan receptor γt+) Th17 cells and produces IL-17 and/or IL-22, which are involved in inflammation and autoimmunity." (PMID 35484967, 2022). "The importance of stimulation of ILC3 for autoimmunity prevention or treatment resides in their FFAR2-mediated IL-22 production and proliferation, but also in the fact that this FFAR2-mediated stimulation will not initiate IFN-γ production." (PMID 34149694, 2021). "Th17 cells are a subset of T helper cells related to autoimmunity and inflammation, which have IL-1β receptors and can secrete cytokines such as IL-17 and IL-22 under the stimulation of IL-1β." (PMID 34093086, 2021). "In spite of the fact that IL-22 has a significant function in autoimmunity and the inflammatory responses of skin, involvement of IL-22 in skin cancer is rarely documented." (PMID 33042126, 2020). "GM-CSF and IL-22 are both emerging as key players in autoimmunity, sometimes more potent than IL-17A in the development of disease." (PMID 25148371, 2014). "Th17 cells, a subset of Th cells involved in autoimmunity and inflammation, possess IL-1β receptors and secrete cytokines such as IL-17 and IL-22 in response to IL-1β stimulation." (PMID 23970818, 2013). "Th17 cells are mediators of inflammation and autoimmunity and secrete IL-17, IL-21, and IL-22." (PMID 36012429, 2022). "In this review, we have focused on the actions of IL-22 on commensal microbiota and discussed circumstances where dysbiosis induces perturbed immune responses that may lead to detrimental inflammation and autoimmunity." (PMID 33003458, 2020). "However, a tight regulation of IL-22 is generally needed, since uncontrolled IL-22 production can lead to the progression of autoimmunity and cancer." (PMID 33003458, 2020). "Th17 cells, a subpopulation of CD4+ T cells, are involved in coordinating host defense and inflammatory responses in autoimmunity, with BATF binding to the promoters of genes related to Th17 differentiation, including IL-17, IL-21, and IL-22." (PMID 38786064, 2024).
Autoimmunity (continued). "IL12 activates type 1 immunity (TH1-defence against viruses and intracellular bacteria, inflammation/autoimmunity, IFN-γ) and IL23 activates type 3 immunity (TH17-defence against extracellular bacteria and fungi, inflammation/autoimmunity, IL22)." (PMID 34659373, 2021). "Of note, patients with autism have increased inflammatory cytokines IL-21, IL-22, IFN-γ, and IL-4 from T cells, decreased antiinflammatory cytokines TGFβ and IL-10, two functional cytokines produced by Tregs, activated T cells, and/or autoimmunity." (PMID 40155813, 2025). "The expression of IL-22 in cancers and autoimmune disorders is various, with IL-17 as siblings but not twins regarding their biological characteristics." (PMID 23236476, 2012). "Although previous studies have indicated that IL-22 secreted by Th22 participates in certain tumorigenicity and autoimmunity, it is not clear whether they are involved in MDS yet." (PMID 23236476, 2012).